CD38 (CD38 molecule)
Diseases named in the same sentence as CD38 in open-access papers (continued):
Sharing a sentence is not in itself a finding about the gene and the disease.
Autoimmunity (30 papers, 2008 to 2026). The occurrence of an immune reaction against the organism's own cells or tissues. "CD38 has an enormous potential to be used as a target to inhibit the chronic inflammatory reactions linked to aging and autoimmunity and to eliminate autoreactive plasma cells that produce potentially harmful autoantibodies." (PMID 34504495, 2021). "M‐B subsets (CD19+CD27+CD38‐) are considered a risk factor for autoimmunity because of their low activation threshold." (PMID 32918534, 2020). "It has been suggested that CD38 deficiency may result in susceptibility to autoimmunity and decreased immune integrity, but further studies in humans are required to analyze the effects of insufficient CD38." (PMID 36678315, 2023). "Contrariwise, CD38 deficiency in murine models has shown enhanced autoimmunity development." (PMID 34769406, 2021). "In line with a role in inflammation, CD38 appears to also play a critical role in inflammatory processes during autoimmunity, although whether CD38 has pathogenic or regulatory effects varies depending on the disease, immune cell, or animal model analyzed." (PMID 33329591, 2020). "Despite the fact of the correlation of CD38 with TSH-R antibodies observed here, we would more likely acquiesce to the hypothesis that CD38 is rather associated with regulation of Bregs function and immune response control, as suggested recently in a mice autoimmunity model." (PMID 34681587, 2021). "Daratumumab, an anti-CD38 monoclonal antibody initially developed for multiple myeloma, demonstrated notable activity across several refractory autoimmune conditions." (PMID 41614907, 2026). "Highlighting the potential contribution of CD38 to age-related diseases, such as autoimmunity, and in the face of inflammatory conditions in aged people." (PMID 41488275, 2025). "Together, these results position CD38 as a key regulator of adaptive immunity in age-related inflammatory diseases, such as autoimmunity, cancer, and inflammation-driven immune dysfunction." (PMID 41488275, 2025). "Given broad spectrum of CD38 expression in immune cells, especially the antibody-secreting plasma B cells, CD38 appears to also play essential roles in processes of inflammation during autoimmunity." (PMID 38765013, 2024). "In several mouse models for autoimmunity and immunopathology, CD38-/- mice demonstrate an ameliorated course in several diseases, such as collagen-induced arthritis model, allergen-induced airway hyperresponsiveness model, and DSS-induced colitis model." (PMID 38982370, 2024). "Previous studies suggested that CD38 was involved in cell differentiation and inflammatory processes and played a key role in the inflammatory process of autoimmunity." (PMID 36778644, 2023). "Apart from its approval for MM treatment, CD38-targeting mAb DARA is gaining attraction as a rescue therapy for autoimmune conditions with PC involvement." (PMID 37419630, 2023). "Ultimately, we propose here a novel therapeutic approach by depleting CD38-positive plasma cells, as the source of the autoimmunity, to treat patients with IgAN." (PMID 35628935, 2022). "In contradiction with these previous reports, some authors have suggested that CD38 plays a role in preventing autoimmunity." (PMID 34769406, 2021). "Several reports have demonstrated that the absence or expression of CD38 modulates the development of autoimmunity." (PMID 33329591, 2020). "Depending on the disease type, immune cell population, or animal model analyzed, several reports indicate that CD38 can either suppress or induce autoimmunity." (PMID 33329591, 2020). "The most important findings and controversies on our current understanding on the role of CD38 in autoimmunity are summarized below." (PMID 33329591, 2020). "The lack of consensus highlights the need of more research in order to understand the biology of CD38 and its contributions to inflammation and autoimmunity." (PMID 33329591, 2020).
Autoimmunity (continued). "CD38−/− mice develop autoimmunity, displaying high levels of anti-nuclear antibodies, anti-double strand DNA auto-antibodies and a reduced survival, and such effects have been related to a defective function of Bregs." (PMID 31783629, 2019). "Anti-CD38 mAbs-mediated PC depletion in autoimmunity and organ transplants is currently under investigation." (PMID 31783629, 2019). "Recent studies demonstrated the presence of a cell subset with CD19+CD20-CD27+CD38+ phenotype that has the ability to secret antibody, either in peripheral blood or in cerebrospinal fluid, in patients with autoimmune disorders, such as neuromyelitis optica spectrum disorder and multiple sclerosis." (PMID 37947190, 2024). "Furthermore, it has been shown that CD38 absence in murine models with autoimmunity enhances the development of the disease." (PMID 34769406, 2021). "In this review, we analyze current knowledge and controversies regarding the role of CD38 during inflammation and autoimmunity and novel molecular tools that may clarify current gaps in the field." (PMID 33329591, 2020). "Thus, anti-CD38 autoimmunity mightindicate a relative protection against beta-cell failure and a lower risk ofinsulin requirement." (PMID 19300526, 2008). "CD38, a membrane ADP-ribosyl cyclase expressed in several cells such as lymphocytes and β-cells, is involved in OXT secretion; targeted disruption of CD38 accelerates autoimmune diabetes in NOD mice by enhancing autoimmunity." (PMID 29867762, 2018). "Ongoing and upcoming clinical trials evaluating BCMA-targeted antibody–drug conjugates, anti-CD38 monoclonal antibodies, and chimeric antigen receptor (CAR) T-cell therapies are expected to substantially reshape treatment landscapes for refractory autoimmunity." (PMID 41614907, 2026). "For that reason, we have reported that lack of CD38 in a B6 genetic background ameliorates autoimmunity in the collagen-induced arthritis model due to decreased iNKT cells in secondary lymphoid organs that were unable to boost a Type 1 helper T cell (Th1) response." (PMID 30257456, 2018). "Thus, it is not surprising that links between CD38 and chronic inflammation or autoimmunity may exist." (PMID 33329591, 2020).
rheumatoid arthritis (29 papers, 2013 to 2026). A chronic, systemic autoimmune disorder characterized by inflammation in the synovial membranes and articular surfaces. "Rheumatoid arthritis similarly showed increased usage of metallothionein, HLA, ICOS/CD38, TPH cells and other activation-associated cGEPs (Q < 0.05)." (PMID 40903640, 2025). "When the metabolism of NAD and its CD38 enzyme are dysfunctional, rheumatic diseases including systemic sclerosis, systemic lupus erythematosus, and rheumatoid arthritis are induced." (PMID 40124370, 2025). "This study aimed to explore the role of CD11b, CD38, and HLA-DR in saliva, linking rheumatoid arthritis (RA) and periodontitis." (PMID 40512337, 2025). "Our research group has found that CD38+ NK cells in the peripheral blood of rheumatoid arthritis (RA) patients play an important role in regulating immune balance." (PMID 38463232, 2024). "For instance, increased infiltration of CD38+ plasma cells has been noted in the synovium of patients with early rheumatoid arthritis." (PMID 39620226, 2024). "C3G reduced CD38+ cell proportion, suppressed rheumatoid arthritis synovial fibroblast (RASF) proliferation, and decreased proinflammatory cytokine secretion." (PMID 37836436, 2023). "CD38 is induced on immune cells in inflammatory diseases such as rheumatoid arthritis, systemic lupus erythematous (SLE), and multiple sclerosis." (PMID 36865257, 2023). "For example, in rheumatoid arthritis CD38 is involved in the regulation of the cellular Treg/Th17 ratio through its expression in NK and NKT cells." (PMID 36618427, 2022). "For example, CD38 is highly expressed in the blood, CD3+ and CD56+ subpopulations of patients with rheumatoid arthritis, and the percentage of CD38+ cells is significantly correlated with RF levels." (PMID 33820568, 2021). "Elevated CD38 expression is observed in rheumatoid arthritis (RA), where higher levels of CD38+ cells correlate with the presence of rheumatoid factors." (PMID 39492834, 2024). "In rheumatoid arthritis (RA), the inhibition of CD38 activation by anti-CD38 monoclonal antibody has been effective to reduce RA symptoms and disease progression." (PMID 36426217, 2022). "Flow cytometry revealed T cell infiltration in the rheumatoid arthritis synovium with differential expression of PD-1, CD45RO, ICOS, TIGIT and CD38." (PMID 36270740, 2022). "Tissues of rheumatoid arthritis (RA) patients exhibit elevations in CD38, too." (PMID 36077708, 2022). "In addition to pathology within the lung, the role of CD38 in rheumatoid arthritis (RA) and collagen-induced arthritis (CIA) has also been evaluated—both diseases demarked by chronic inflammation." (PMID 31878283, 2019). "CD38+ NK cells are overabundant in rheumatoid arthritis (RA)." (PMID 31661005, 2019). "Synovial tissue specimens (normal synovium, n=15; orthopedic arthropathies, n=6; osteoarthritis, n=26; early undifferentiated arthritis, n=10; rheumatoid arthritis, n=26; chronic septic arthritis, n=11) were stained for CD15, CD68, CD3, CD20, and CD38." (PMID 23951325, 2013).
Sepsis (29 papers, 2015 to 2025). Sepsis is defined as life-threatening organ dysfunction caused by a dysregulated host response to infection. "To explore the underlying reasons for enrichment of CD38high monocytes in sepsis, we re‐analyzed our RNA‐seq data and found a significant reduction in CD38 expression in monocytes upon CD38 inhibition." (PMID 40145840, 2025). "CD25 on IgD- CD38- B cell was identified as the mediation immunological trait for the causal effect of tea consumption on puerperal sepsis." (PMID 41137229, 2025). "Accumulated evidence indicates that CD38 plays an important role in many inflammatory diseases, such as lung injury associated with sepsis." (PMID 36998049, 2023). "From these results, we can draw a conclusion that TLR4 mutation can mitigate CD38 deficiency which aggravates liver injury in sepsis by GSDMD-mediated pyroptosis." (PMID 33860064, 2021). "Blocking this pathway through lentiviral-mediated CD38 knockdown or cADPR antagonism protected the hippocampus from apoptosis, oxidative stress and morphological damages associated with sepsis." (PMID 31963337, 2020). "The effect of tea consumption on puerperal sepsis risk was mediated by CD25 on IgD- CD38- B cell." (PMID 41137229, 2025). "Therefore, Daph can up-regulate CD38 to alleviate LPS-induced apoptosis in lung injury, and further research is needed to study the possible role of apoptosis in sepsis-associated lung injury." (PMID 36998049, 2023). "ERK1/2 and NF-kB/p65 could be then highly activated and play a crucial function in the inflammatory response in sepsis in CD38 deficiency." (PMID 36077708, 2022). "CD38 could activate MAPK/NF-kB signaling pathway in mice sepsis caused by pulmonary injury induced by E. coli, leading to the release of inflammatory cytokines, such as IL-1b, and inflammasome NLRP3." (PMID 36077708, 2022). "Our data revealed that CD38 may serve as a novel cell-surface indicator of exhausted monocytes that may sustain and propagate pathogenic inflammation associated with sepsis." (PMID 34777396, 2021). "In accordance with the expected results, we observed a significant increase in the expression levels of pyroptosis-related markers in the liver of CD38-deficient septicemia mice, such as NLRP3, cleaved caspase-1, IL-1β, and IL-18, accompanied by the increase in cleaved caspase-3." (PMID 33860064, 2021). "And in this study, we observed severe pyroptosis and serious damage of the liver in septicemia-related liver injury in CD38-deficient mice, whereas both pyroptosis and damage of the liver can be significantly reversed in TLR4 mutant mice, accompanied by the decrease in NLRP3 and GSDMD." (PMID 33860064, 2021). "Therefore, we investigated the role of pyroptosis in the liver injury of septicemia aggravated by CD38 deficiency." (PMID 33860064, 2021). "Taken together, upregulation of TLR4 in the CD38−/− mice could cause an aggravated kidney injury in sepsis induced by LPS through promotion of the IFN-γ expression." (PMID 30915370, 2019). "Therefore, the kidney is particularly susceptible to the effects of CD38 ligation in sepsis and may be a primary source of IL-6 production." (PMID 39568061, 2025). "Further research using human samples is necessary to clarify the involvement of circulating CD31 in CD38 ligation during sepsis." (PMID 39568061, 2025). "We also confirmed increased renal Il6 production following CD38 ligation in an additional mouse model of sepsis induced by faecal suspension intraperitoneal injection." (PMID 39568061, 2025). "Collectively, these results suggest that the CD38-related signalling observed in mice with sepsis is consistent with that observed in humans." (PMID 39568061, 2025). "Our findings elucidate the implications of CD38 ligation in an LPS-induced sepsis model and uncover shared signalling pathways between mice and human sepsis." (PMID 39568061, 2025).
Sepsis (continued). "The elevated expression of Il6 mRNA in the renal stromal cells and increased NAMPT expression in CD38-positive macrophages represent novel findings in both mice and humans with sepsis." (PMID 39568061, 2025). "Subsequently, CD38 ligation was induced by administering a well-established agonistic anti-CD38 antibody (clone NIMR-5) to the LPS-induced sepsis model." (PMID 39568061, 2025). "We next examined the phenotype of sepsis in vivo through pharmaceutical inhibition of CD38 at different time points." (PMID 40145840, 2025). "This study uncovered the NAMPT signalling pathway from the CD38-positive macrophages to the renal stromal cells in a mouse model of sepsis and validated these findings in human samples." (PMID 39568061, 2025). "A previous report, using LPS administration as a sepsis model, demonstrated that CD38 promotes the expression of proinflammatory cytokines, including IL-1β, IL-6, and IL-12." (PMID 41488275, 2025). "Sepsis patients tended to have a slightly higher frequency of CD38+, CD69+ and lymphocyte activation gene 3 (LAG‐3)+ MAIT cells compared with non‐sepsis patients, although not significantly so." (PMID 40041474, 2025). "Subsequently we induced CD38 ligation using a well-established agonistic anti-CD38 antibody in a mouse model of LPS-induced sepsis." (PMID 39568061, 2025). "This study elucidated the implications of CD38 ligation in sepsis and identified common signalling pathways in mice and humans with sepsis." (PMID 39568061, 2025). "In a CLP sepsis mouse model, Cd38‐kncokout and pharmaceutical early intervention of CD38 reduced the disease phenotype of sepsis mouse model, making it a promising therapeutic target to treat patients with sepsis." (PMID 40145840, 2025). "Meanwhile, we further analyzed independent cohorts from published bulk‐expression studies of monocytes in sepsis, and found the mRNA expression levels of CD38 were significantly higher in patients with sepsis than in healthy controls." (PMID 40145840, 2025). "This is the first study to reveal significant IL-6 production in the renal stromal cells of mice with CD38-ligated sepsis and humans with severe sepsis." (PMID 39568061, 2025). "Targeting CD38 therapy markedly reduces inflammatory response in primary monocytes and in sepsis mice model." (PMID 40145840, 2025). "In conclusion, we uncovered the implications of CD38 ligation in an LPS-induced sepsis model and identified shared signalling pathways in both mice and humans with sepsis." (PMID 39568061, 2025). "Using an in vivo cecal ligation and puncture (CLP) sepsis model, Cd38 ablation significantly improved the survival rate of septic mice and reduced serum cytokines." (PMID 40145840, 2025). "Activated macrophages, pivotal for driving the immune response in sepsis, express high levels of CD38." (PMID 39568061, 2025). "Conventional flow cytometry revealed significantly elevated CD38 expression levels of monocyte(moCD38) in sepsis patients." (PMID 40145840, 2025). "Although the circulating levels of its ligand, CD31, increase in sepsis, the functions of CD38 and its ligation remain elusive." (PMID 39568061, 2025). "Previous studies using CD38 knockout mice have demonstrated amelioration of sepsis-induced neuroinflammation and exacerbation of lung, liver and kidney injury." (PMID 39568061, 2025). "The top three peripheral immune cell subtypes pinpointed by ML analysis in discriminating sepsis from HCs were CD38+CD8+T cells, PD-1+NK cells, and HLA-DR+ CD8+T cells." (PMID 38953031, 2024). "And studies have been reported that blocking CD38 pathway can protect hippocampal cells from apoptosis, oxidative stress and ultrastructural damage in sepsis rats." (PMID 36998049, 2023). "Recently, it was demonstrated that CD38 deficient mice increased the expression of IL-1β and MCP-1 and aggravated lung injury through TLR4/ERK/NF-κB pathway in sepsis." (PMID 36998049, 2023).